DAZL (deleted in azoospermia like)
Description:
RNA-binding protein, which is essential for gametogenesis in both males and females. Plays a central role during spermatogenesis. Acts by binding to the 3'-UTR of mRNA, specifically recognizing GUU triplets, and thereby regulating the translation of key transcripts (By similarity).
Synonyms: DAZH; DAZL1; DAZLA; SPGYLA; MGC26406
Tractability: PROTAC: ubiquitination databases record sites on it.
Gene: Protein-coding gene on chromosome 3 (16,586,792 to 16,670,306, reverse strand). Ensembl gene ENSG00000092345.
Subcellular location: Cytoplasm; Nucleus
Gene Ontology:
Molecular function: protein binding; translation activator activity; RNA binding; mRNA 3'-UTR binding; nucleic acid binding
Biological process: positive regulation of translational initiation; 3'-UTR-mediated mRNA stabilization; germ cell development
Cellular component: cytoplasm; protein-containing complex; nucleus
Genetic constraint (gnomAD): Loss-of-function variants: 1 observed, 23.69 expected, observed/expected ratio (o/e) 0.0422, 90% interval 0.014 to 0.2. The upper end of that interval is the gene's LOEUF score, 0.2, which puts it in group 1 of 6, group 1 being the genes least tolerant of losing a copy. Missense variants: 187 observed, 214.36 expected, observed/expected ratio (o/e) 0.87, 90% interval 0.77 to 0.99. Synonymous variants: 83 observed, 67.69 expected, observed/expected ratio (o/e) 1.23, 90% interval 1.03 to 1.47.
Homologues: Orthologues: chimpanzee DAZL (99% identical), macaque DAZL (98% identical), dog DAZL (93% identical), mouse Dazl (88% identical), rat Dazl (88% identical), tropical clawed frog dazl (51% identical), zebrafish dazl (33% identical), Caenorhabditis elegans daz-1 (24% identical), Drosophila melanogaster bol (16% identical). Paralogues in human: DAZ2 (62% identical), DAZ4 (61% identical), DAZ3 (61% identical), DAZ1 (60% identical), BOLL (30% identical).
Diseases named in the same sentence as DAZL in open-access papers:
DAZL is named in the same sentence as 29 diseases in open-access papers, as found by Europe PMC text mining. Sharing a sentence is not in itself a finding about the gene and the disease. The quoted sentences say what the papers report.
Azoospermia (33 papers, 2013 to 2025). Absence of any measurable level of sperm,whereby spermatozoa cannot be observed even after centrifugation of the semen pellet. "The DAZL protein has shown significant clinical associations with human idiopathic azoospermia and primary ovarian insufficiency (POI), indicating its potential as a promising therapeutic target." (PMID 41249172, 2025). "DAZL is a strong candidate for the azoospermic factor, and various polymorphisms of DAZL have been implicated to be associated with azoospermia." (PMID 34296486, 2021). "The loss of the DAZL gene led to the decrease of germ cell numbers before birth, and the loss of DAZL protein led to azoospermia or severe oligospermia." (PMID 35145544, 2021). "High-risk genes mostly identified include Y chromosome-linked genes, X-linked candidate genes and the deleted in azoospermia-like (DAZL) gene, which is an autosomal homologue of the Y-chromosomal deleted in azoospermia (DAZ) gene cluster." (PMID 29263816, 2016). "The DAZL genes are strong candidates for azoospermia factor, one of the most common genetic causes of male infertility." (PMID 25644284, 2015). "In humans, loss of Y-chromosomal DAZL genes results in oligozoospermia or azoospermia." (PMID 25644284, 2015). "Interestingly, we identified meiotic proteins a priori unrelated to the UPS such as DAZL (deleted in azoospermia), SPAG1 (Sperm-associated antigen 1), SPATA5/20 (Spermatogenesis-associated protein 5/20), the tudor domain proteins TDRD1/6/9, MAEL (repressor of transposable elements), and RNF17." (PMID 31437213, 2019). "DZIP1 encodes a DAZ (a protein deleted in azoospermia) interacting protein, there is strong evidence that the DAZ and a closely related homolog, DAZL (DAZ-like), are required in early germ cell development to maintain initial germ cell populations." (PMID 37854191, 2023). "Most of the mRNAs bound to translational ribosomes in mouse oocytes contain motifs for the RNA-binding proteins, CPEB1 and DAZL (deleted in azoospermia-like)." (PMID 36497033, 2022). "DAZAP1 was initially identified as an important binding partner of DAZ (deleted in azoospermia) and DAZL (deleted in azoospermia like), required for not only spermatogenesis but also the normal growth and development of mammals." (PMID 36242590, 2022). "DAZL stands for “deleted in azoospermia like,” and it codes for a RNA-binding protein that is localized to the nucleus of spermatogonia, but relocates to the cytoplasm during meiosis, where it persists in spermatids and spermatozoa." (PMID 33995471, 2021). "DAZL (deleted in azoospermia-like), a germ cell-specific RNA-binding protein, is essential for developing PGCs." (PMID 34384478, 2021). "Targeted (ZD+ZD-) PGCs were injected into transgenic surrogate host chicken embryos containing an inducible Caspase9 (iCaspase) targeted to the germ cell-specific DAZL locus (deleted in azoospermia)." (PMID 33658372, 2021). "One of these multicopy gene families is DAZ (deleted in azoospermia, MIM*400003), which evolved from the autosomal gene DAZL (deleted in azoospermia-like, MIM*601486)." (PMID 31973052, 2020). "Deleted in azoospermia-like (DAZL) protein, a homolog of the deleted in azoospermia (DAZ), is expressed in the nuclei and cytoplasm of germ cells at all stages of spermatogenesis in humans, mice, and pigs." (PMID 29362488, 2018). "DAZL (deleted in azoospermia-like) is one of the RBPs required for the sexual differentiation of primordial germ cells and for the progression of meiosis in ovulated oocytes." (PMID 29883445, 2018). "Immunofluorescence data revealed that some subpopulations of the hfSDSCs exhibited positive expression of hGCLCs biomarkers including DAZL (Deleted in Azoospermia-like) and VASA." (PMID 26347377, 2015). "Detection of DAZ (deleted in azoospermia), DAZL (DAZ-like) and protamine 2 (PRM2) mRNA in testicular samples was shown to be an informative tool for spermatogenesis evaluation." (PMID 23675907, 2013).
Azoospermia (continued). "The DAZL gene belongs to the gene family of DAZ (Deleted in Azoospermia)." (PMID 37570330, 2023). "The abnormal expression of DAZL affects about 10% of males with azoospermia or oligozoospermia." (PMID 29362488, 2018). "In male reproduction, similar mutations could underlie cases of non-obstructive azoospermia characterized by meiotic arrest, as DAZL/PABPC1-dependent translation is crucial for spermatocyte survival." (PMID 41249172, 2025). "Moreover, DAZL mRNA (also known as deleted in azoospermia like) associated with late germ cells was not present in our hPGCLCs-TS and control cell lines." (PMID 34831322, 2021). "The relevance of DAZL has been demonstrated in knockout mice, where embryos display a reduced expression of GC-specific genes and postnatal males present an impairment in the progression from A to A1 spermatogonia and meiotic arrest resulting in azoospermia and sterility." (PMID 34113673, 2021). "The formation of the SC and progression of meiosis is dependent on RNA binding proteins, of which the best characterized is DAZL (deleted in azoospermia-like) and its homologues DAZ (deleted in azoospermia) and BOLL (Bol-like) (reviewed in Refs." (PMID 37171807, 2023). "Deleted azoospermia (DAZ) is one of the RNA-binding proteins of germ cells that includes DAZ, deleted azoospermia-like (DAZL), and BOULE." (PMID 34556135, 2021). "Dazl (Deleted in azoospermia-like), a member of the DAZ (Deleted in Azoospermia) gene family, which is also identified as a marker for germ cell identification." (PMID 32682409, 2020). "In addition, BOULE (also called BOLL), a member via RNA-binding protein of the deleted in azoospermia (DAZ) gene family, complements the functions of DAZL and has been reported to be important for meiotic division and spermatogenesis." (PMID 34113673, 2021).
infertile (20 papers, 2006 to 2024). "In mice, loss of DAZL expression results in infertility in both genders, with post migratory germ cell apoptosis and a final block in meiosis." (PMID 37570330, 2023). "DAZL, which is crucial for normal spermatogenesis, plays an important role in primordial germ cell formation, and genetic loss of DAZL causes infertility in both sexes of mice." (PMID 36091762, 2022). "Heterozygous and homozygous missense variants in DAZL were reported in infertile men and woman associated with secondary amenorrhea." (PMID 33095795, 2020). "The RNA binding protein DAZL has an essential role in translational control during gametogenesis, and its absence or altered function is associated with infertility in several organisms, including humans." (PMID 26989066, 2016). "Consistent with the phenotype in DAZL-deficient rats, spermatogenesis defects in DAZL-deficient mice mirror many forms of male-factor infertility caused by Y-chromosome microdeletions of human DAZ genes." (PMID 19621088, 2009). "We, therefore, analyzed 147 infertile and 140 normozoospermic fertile controls from rural areas of Tamil Nadu, South India, to assess the phenotypic effect of DAZL mutations." (PMID 20300286, 2008). "However, heterozygous and homozygous missense substitutions in DAZL gene were previously identified in infertile woman associated with secondary amenorrhea." (PMID 38649916, 2024). "Mutations in DAZL gene have been associated to infertility in man and women." (PMID 31029102, 2019). "In conclusion, our data suggest that aberrant DNA methylation of the H19-DMR and the DAZL gene promoter is associated with single-phenotype defects in sperm production/function in infertile men and further studies are warranted to address the role of epigenetic mechanisms in male infertility." (PMID 24015185, 2013). "In addition, The abnormalities of DAZL promoter DNA methylation pattern and its expression are closely associated with spermatogenesis disorders in patients with infertility." (PMID 24015185, 2013). "Detailed histological analysis of DAZL-deficient rat testes revealed an apparently intact spermatogonial stem cell compartment, but clear failure to produce mature haploid gametes resulting in infertility." (PMID 19621088, 2009). "A role for NRF1 during human spermatogenesis has also been suggested since mutations in the promoter regions of a key meiotic gene, DAZL, lead to the loss of NRF1 binding and are associated with infertility." (PMID 31350280, 2019). "Our analyses of LINE1 transposons indicate that abnormal methylation of the H19-DMR and the DAZL gene promoter specifically occurred in OZ and/or AZ sperm of infertile men." (PMID 24015185, 2013). "Defining molecular mechanisms linked to the enhanced colonization of donor spermatogonia in DAZL-deficient recipients will be of potential clinical interest because it could lead to new therapeutic strategies for optimizing the efficiency at which donor germ cells engraft testes of infertile men." (PMID 19621088, 2009). "Analysis of exon 3 of the DAZL gene in a total of 287 men, including 147 infertile and 140 normozoospermic control men of Tamil Nadu, South India, revealed the complete absence of the previously reported A386G mutation in the DAZL gene." (PMID 20300286, 2008). "However, our study differentiated OZ (n = 20) and AZ (n = 20) from infertile patients, and further confirmed the correlation of AZ and OZ with abnormal methylation of the DAZL promoter region." (PMID 24015185, 2013). "There has been no study on infertile men from North India showing possible correlation between A386G polymorphism of the DAZL gene with idiopathic male infertility." (PMID 19881148, 2009). "Reported instances of positive association of DAZL gene mutations with infertility in men have been found in a Taiwanese population but not in Caucasians." (PMID 20300286, 2008). "In addition, further studies may shed a light on the role of DAZL in human infertility." (PMID 16884537, 2006).
infertile (continued). "In addition, gain of methylation in spermatogenesis-related gene promoters, including DAZL, PIWIl2 and TDRD1, is observed in spermatozoa and testicular samples from infertile human patients." (PMID 27880848, 2016). "There has been no study on infertile men from Tamil Nadu, South India, that has attempted to demonstrate the role of DAZL gene in male infertility." (PMID 20300286, 2008).
male infertility (10 papers, 2008 to 2025). The inability of the male to effect fertilization of an ovum after a specified period of unprotected intercourse. "In this study, we tried to find the association of some SNPs of PYGO2, PRM1, PRM2, and DAZL genes with male infertility." (PMID 36197138, 2022). "The Gene Ontology (GO) analysis of biological process categories showed that the target genes of tRF-Val-AAC-010 are involved in spermatogenesis and mutation in CCDC155 and DAZL genes have also been detected in male infertility patients." (PMID 35869479, 2022). "Recently, a number of molecular epidemiological studies have been conducted to examine the association between DAZL polymorphisms and male infertility in diverse populations." (PMID 24717865, 2014). "Our analysis suggests that further exploration of the true association between DAZL polymorphism and male infertility is demanded." (PMID 24717865, 2014). "There are, however, no other reported instances of a positive association of A386G polymorphism of the DAZL gene with idiopathic male infertility." (PMID 19881148, 2009). "This study aims to find out the possible association between A386G (T54A) polymorphism of the autosomal gene, DAZL and idiopathic male infertility in patients from North India.Case-control study." (PMID 19881148, 2009). "To investigate this, we disrupted alternative splicing of Dazl by generating DAZL short isoform only mice via deletion of the DAZL exon 8 and found that the resulting loss of DAZL_FL led to male infertility, characterized by extensive spermatocyte apoptosis and arrest of spermatid development." (PMID 41249172, 2025). "Altered methylation of the DAZL promoter has been associated with male infertility." (PMID 26989066, 2016). "Our meta-analysis suggests that DAZL has a relationship with male infertility, but the exact molecular mechanisms of how the variant T54A (located on exon 3) affects male infertility is unknown." (PMID 24717865, 2014). "This study was performed to investigate the correlation of some single nucleotide polymorphisms of PYGO2, DAZL, PRM1, and PRM2 genes with male infertility in idiopathic cases among the Iranian population." (PMID 36197138, 2022). "In humans some very limited studies have been carried out on the DAZL gene and its role in male infertility." (PMID 20300286, 2008). "As a result, DAZL has always been seen as a promising candidate for male infertility." (PMID 24717865, 2014). "Last but not the least, novel missense mutations in DAZL and DAZL's role of epigenetic mechanisms in male infertility should be taken into future studies." (PMID 24717865, 2014). "However, the small sample size is a limitation of this study, and future studies of male infertility mechanisms in a larger cohort is needed to confirm the role/utility of DAZL promoter methylation as an indicator of male infertility." (PMID 24015185, 2013). "Abnormal DNA methylation of the DAZL promoter might represent an epigenetic marker of male infertility." (PMID 24015185, 2013). "Therefore, we proposed that abnormal pattern of DNA methylation in the DAZL gene promoter (i.e., clones with >20% methylation) may represent an epigenetic indicator of male infertility." (PMID 24015185, 2013).
premature ovarian failure (3 papers, 2007 to 2017). "In a second study a patient with premature ovarian failure at age 34 was found to contain a homozygous mutation of DAZL (Arg to Gly at 115) in a region of the protein critical for RNA binding." (PMID 18088417, 2007).
glioblastoma (2 papers, 2020 to 2023). The most malignant astrocytic tumor (WHO grade IV). "The knock-out of DAZL in the glioblastoma cell line with CRISPR/Cas9 gene-editing technology found that DAZL contributed to the tumorigenicity of glioblastoma by reducing cell stemness." (PMID 36672345, 2023).
oligospermia (2 papers, 2009 to 2021). Decreased number of spermatozoa in the semen. "Thus A386G in DAZL appears to be strong risk factor for azoo-/oligospermia." (PMID 19881148, 2009). "DAZL, an autosomal gene (chromosome 3p24), has a high degree of homology with the Y-chromosomal DAZ whose deletion is one of the main genetic causes for azoo/oligospermia." (PMID 19881148, 2009).
asthenozoospermia (1 paper, 2021). "Higher DAZL methylation was found in asthenozoospermia and oligozoospermia men37." (PMID 33542261, 2021).
breast carcinoma (1 paper, 2013). "DAZL is only expressed in IGCNU but not for example in breast cancer cells and is therefore regarded as germ cell origin of these cells." (PMID 23969837, 2013).
colon cancer (1 paper, 2017). "DAZL expression was increased by 5-AC treatment in one of two colon cancer lines and two of three ovarian cancer lines tested." (PMID 28622390, 2017).
female infertility (1 paper, 2020). Diminished or absent ability of a female to achieve conception. "Although DAZL plays a key role in human and animal germ cells, it seems that pathogenic variants are a rare cause of male and female infertility." (PMID 33095795, 2020).
germ cell tumor (1 paper, 2022). A benign or malignant, gonadal or extragonadal neoplasm that originates from germ cells. "Considering the proliferation inhibition and teratoma suppression capacity of DAZL, our findings may be useful for developing therapeutic treatments for patients suffering from germ cell tumors." (PMID 36273819, 2022).
glioma (1 paper, 2022). A benign or malignant brain and spinal cord tumor that arises from glial cells (astrocytes, oligodendrocytes, ependymal cells). "Our earlier study revealed that knockdown of DAZL inhibited tumour formation and increased the therapeutic sensitivity of cultured human glioma cells." (PMID 36435765, 2022). "Our findings showed that germ cell-like cells were present in cultured glioma cells and glioma tissues and that deletion of DAZL repressed both PGC-like cell formation and tumour initiation in human glioma cell lines." (PMID 36435765, 2022). "Since DAZL−/− glioma cells were not viable in culture possibly attributed to a crucial role of DAZL or germ cell fate in immortality of tumour cells, U251- DAZL+/−, LN229-DAZL+/− and A172mut- DAZL+/− cells were studied." (PMID 36435765, 2022).
gonadal teratoma (1 paper, 2022). A teratoma that arises from the testis or ovary. "Recent studies have shown that DAZL deletion causes spontaneous gonadal teratomas in mice and pigs, whereas an overexpression of DAZL in hPGC-like cells (hPGCLCs) reduces the expression of pluripotency markers, including OCT4 and NANOG." (PMID 36273819, 2022).
melanoma (1 paper, 2024). A malignant, usually aggressive tumor composed of atypical, neoplastic melanocytes. "Some of the top upregulated genes included Interferon Induced Transmembrane Protein 3 (IFITM3), Preferentially Expressed Antigen in Melanoma (PRAME), and Deleted in Azoospermia-like (DAZL)." (PMID 38468866, 2024).
oligoasthenoteratozoospermia (1 paper, 2020). A form of male infertility that is characterized by a combination of low number or oligozoospermia, poor motility or asthenozoospermia, and abnormal shape or teratozoospermia of sperms. "According to previous studies on patients with oligoasthenoteratozoospermia, there was an increase in methylation defects of DAZL promoters." (PMID 33013270, 2020).
ovarian failure (1 paper, 2006). "Recently, we showed that there are several common polymorphisms within the DAZL gene that are associated with age at ovarian failure/menopause and sperm count." (PMID 16884537, 2006).